INS (insulin)
Diseases named in the same sentence as INS in open-access papers (continued):
Sharing a sentence is not in itself a finding about the gene and the disease.
Insulin resistance (continued). "In this study, we aimed to determine whether TGFβ1 is in part responsible for the development of insulin resistance and/or aberrant insulin signalling, previously observed in the skeletal muscle and myotubes of women with PCOS." (PMID 34707569, 2021). "Insulin resistance precedes type 2 diabetes and occurs when insulin signaling is impaired." (PMID 33925459, 2021). "After eight weeks on a fructose-rich diet, the rats presented some features of the metabolic syndrome, namely there was a tendency for higher serum concentration of triglycerides, insulin and high score for the homeostasis model assessment for insulin resistance (HOMA)." (PMID 35008629, 2021). "In the present study, ectopic triglyceride accumulation in the muscles of ovariectomized rats increased, which may indicate the involvement of an important mechanism in the impairment of insulin signaling in muscles and the development of insulin resistance." (PMID 33926097, 2021). "However, insulin levels tended to be reduced in the baccharin-treated group, and the homeostasis model assessment of insulin resistance (HOMA-IR) index was significantly improved." (PMID 34203569, 2021). "For this reason, it would seem reasonable to verify the cut off values for fasting insulin, insulin resistance, and hyperinsulinemia which may affect investigation of RH." (PMID 33916952, 2021). "The increased mRNA levels of PPAR-α are also most likely related to the reduced insulin resistance found in the skeletal muscle of old rats treated with the nutraceutical since this transcription factor is reported to play a key role in muscle insulin sensitivity." (PMID 34356299, 2021). "The impairment of central insulin action can occur also as a result of disturbances in the IR signal transduction, particularly in the activation states of IR and signaling molecules, thereby giving rise to insulin resistance." (PMID 33810179, 2021). "Twelve weeks of curcumin treatment in subjects with a high risk of developing T2DM lowered serum insulin levels and insulin resistance, but not fasting blood glucose." (PMID 34970150, 2021). "This indicates that insulin resistance may have an etiological role in the progression of glaucomatous neurodegeneration and thus enhancing insulin sensitivity may serve as a potential therapeutic modality for glaucoma." (PMID 33925119, 2021). "Insulin secretory capacity was found to increase during pregnancy to counteract increased insulin resistance, a process that may be important for maintaining NGT." (PMID 33776619, 2021). "However, there are studies with HR patients who had insulin resistance and significant impairment of insulin secretion." (PMID 33916952, 2021). "In 1959, Rosalyn Yalow, the second woman to win a Nobel Prize in Physiology or Medicine, developed the radioimmunoassay to accurately determine the blood insulin levels in humans, which confirms that patients with T2DM actually have high blood insulin levels, indicating insulin resistance." (PMID 34440929, 2021). "Smaller adipocytes retain their insulin sensitivity, while hypertrophied adipocytes are likely to become insulin resistant and secrete proinflammatory cytokines, such as tumor necrosis factor-alpha (TNFα) and interleukin 6 (IL-6), which can also induce insulin resistance in other tissues." (PMID 33671850, 2021). "T2DM is characterized by impaired insulin secretion and insulin resistance." (PMID 35141228, 2021). "Due to the improvement effect of cinnamon on the insulin sensitivity, it seems that it could be advantageous in the modification of ovarian hormones and androgens by mitigating insulin resistance." (PMID 34627352, 2021). "Beta cell stress and insulin resistance is a clearly documented phenomenon that occurs after brain death and which may be accountable for the need for insulin to manage hyperglycaemia following brain death." (PMID 33665687, 2021).
Insulin resistance (continued). "In animal models, insulin resistance, and associated hyperinsulinemia is associated with selective insulin resistance in the vasculature; insulin signaling via Phosphoinositide 3-kinase (PI3K) is impaired but insulin signaling via mitogen-activated protein kinase (MAPK) signaling is increased." (PMID 34760952, 2021). "Using this application of DXA would, thus, be theoretically advantageous in measuring the effects of subtle changes in body fat composition on insulin resistance and markers of metabolic syndrome such as fasting insulin, blood glucose, cholesterol, triglyceride levels, and blood pressure." (PMID 34072554, 2021). "To investigate whether DHM ameliorated insulin resistance induced by inflammation, we measured the level of inflammatory cytokines in adipose tissue and insulin sensitivity in mice." (PMID 34650665, 2021). "We have previously shown that muscle insulin resistance does not change during the first 6 months of weight loss although hepatic insulin sensitivity completely normalizes." (PMID 33925808, 2021). "In the development of obesity‐induced insulin resistance, mounting evidence indicates that excessive Drp1‐mediated mitochondrial fission is negatively correlated with skeletal muscle insulin action and whole‐body insulin sensitivity." (PMID 33904649, 2021). "Initially, insulin production is increased to compensate for the insulin resistance, then insulin production may gradually decrease and produce chronic hyperglycemia." (PMID 34842818, 2021). "Compared to the mice fed a standard fat diet, the HFD-induced type 2 diabetic mice exhibited an obvious increase in body weight, as well as hyperglycemia, insulin resistance characterized by decreased glucose intolerance, insulin sensitivity, and increased serum insulin." (PMID 34307690, 2021). "Similarly, the amplified production of reactive oxygen species has harmful regulation of insulin signaling cascade leading to β-cell dysfunction, mitochondrial dysfunction, decreased insulin gene expression, impaired glucose tolerance, and insulin resistance." (PMID 33987444, 2021). "Indeed, classic PCOS is accompanied by abdominal obesity, increased levels of LH and LH/FSH ratio, increased level of androgens, and elevated insulin and insulin resistance." (PMID 33894770, 2021). "Furthermore, a number of studies have demonstrated a correlation between dementia and metabolic changes, such as insulin resistance (impaired intracellular insulin functioning) and glucose imbalance." (PMID 33945675, 2021). "Some scholars believed that insulin resistance has appeared in early onset of type 2 diabetes, to maintain normal blood glucose levels, the islet beta cells continuously increase the secretion of insulin to compensate, and the insulin secretion after reaching the maximum level will decrease." (PMID 34026064, 2021). "In those type 2 DM patients, the secretion of insulin is not low or even higher than the healthy population and the main cause is that the body is not sensitive to insulin, that is, insulin resistance." (PMID 34423045, 2021). "The whole-body insulin resistance possibly promoted by ANKRD55 would endorse the insulin resistance stimulated by cytokines release from visceral fat and the impaired glucose-stimulated insulin secretion in pancreatic β cells mediated by the significant gene TSHZ1." (PMID 35058972, 2021). "Furthermore, was found that low dose GH therapy can ameliorate relation between OS and insulin resistance in GHD condition also improving insulin sensitivity." (PMID 33793606, 2021). "Butyrate functions are multiple but seem inconsistently varying: from plasma glucose reduction, improved insulin sensitivity, and glucose homeostasis, sustaining body weight and adiposity to other less advantageous effects like insulin resistance (IR) and lipid build-up." (PMID 34211580, 2021).
Insulin resistance (continued). "An animal study with fructose-rich chow-fed rats showed that Dioscorea, one of the components of LWDHW, could reduce insulin resistance and improve insulin sensitivity." (PMID 34457016, 2021). "Also in vivo studies previously reported a positive correlation between insulin sensitivity and lean body mass, and multiple papers reported that insulin resistance accelerates muscle protein degradation and inhibits protein synthesis." (PMID 34707570, 2021). "Indeed, AdipoR1 and AdipoR2 were found to regulate insulin sensitivity in insulin target tissues, and are important in the pathophysiology of insulin resistance." (PMID 34395490, 2021). "Of the glucose metabolism indicators, most (k=27) reported on fasting glucose, with only 13 reporting fasting insulin, and 7 reporting composite indicators of beta-cell function or insulin resistance (ie, measures from homeostatic model assessment, HOMA or HOMA-2)." (PMID 32269058, 2021). "When the body produces insulin resistance, its sensitivity to insulin decreases." (PMID 34722505, 2021). "AMPK functions as a central regulator of energy utilization and its dysfunction is associated with the onset of obesity, disruptions in glucose homeostasis, and the development of insulin resistance in insulin-sensitive tissues such as liver and skeletal muscle." (PMID 34502525, 2021). "But most T2DM patients display damaged not only insulin production, but also insulin resistance." (PMID 33450223, 2021). "The IKKβ/NF-κB pathway, one of the classical inflammatory pathways, releases a large number of inflammatory cytokines, thus leading to the failure of target organs, including liver, muscles, and pancreas, to respond normally to the action of insulin, resulting in insulin resistance." (PMID 34262422, 2021). "Insulin increases the activity of tyrosine aminotransferase, an enzyme that catalyzes tyrosine transamination and while in insulin resistance, circulating insulin may maintain adequate glucose metabolism, tyrosine breakdown may be affected." (PMID 34823524, 2021). "As insulin resistance is a major pathophysiologic abnormality of T2D, insulin-sensitizing agents that could restore insulin resistance and control hyperglycemia in T2D patient, has been interested in therapeutic approach." (PMID 33819291, 2021). "Insulin resistance leads to reduced glucose-uptake response in spite of high insulin levels." (PMID 33679617, 2021). "Insulin also promotes phosphorylation of IRS-1 on Ser307 in human skeletal muscle during a hyperinsulinemic-euglycemic clamp suggesting that chronic hyperinsulinemia further induces insulin resistance." (PMID 34943997, 2021). "Moreover, TN expression is increased in mouse adipocytes with the insulin-resistance state induced by a high-glucose plus insulin medium, and in insulin-resistant Swedish male individuals, compared to the control group." (PMID 34371822, 2021). "The whole-body insulin sensitivity index (WBISI) derived from an oral glucose tolerance test (OGTT) provides reasonable estimates of insulin sensitivity and insulin resistance and has been validated as good surrogate measures of insulin resistance in obese children and adolescents." (PMID 34485526, 2021). "Clear evidences point to GCs as potent activators of insulin resistance and inhibitors of insulin secretion, but recent evidences also identified inter-organ communications, at least in mice, linking GC-induced insulin resistance with improved insulin secretion." (PMID 33435513, 2021). "Collectively, this presents the possibility that aberrant TGFβ signalling could induce insulin resistance via direct dysregulation of insulin signalling or by negatively regulating the function and composition of the skeletal muscle ECM." (PMID 34707569, 2021). "The role of vitamin D in insulin secretion and improving insulin resistance has been demonstrated." (PMID 34505755, 2021).
Insulin resistance (continued). "The findings in our study imply that the interaction between hypertensive status and insulin resistance leads to arterial stiffness progression, which means that people with hypertension should pay close attention to insulin resistance indexes to prevent artery stiffness." (PMID 34229681, 2021). "Thus, hepatic loss of IDE function in the setting of diet-induced obesity enhanced β-cells function, leading to increased insulin secretion and hyperinsulinemia to help counteract hepatic insulin resistance." (PMID 33477364, 2021). "Compared to women with normal plasma glucose responses to carbohydrate ingestion, women with clinically significant glucose intolerance often demonstrate both increased insulin resistance and impaired insulin release and are diagnosed with gestational diabetes mellitus (GDM)." (PMID 35046934, 2021). "It is a good practice to continue metformin when initiating insulin as by reducing insulin resistance, metformin may reduce insulin dose requirements and prevent weight gain." (PMID 33098260, 2021). "The findings of this study indicated that thujone can ameliorate palmitate oxidation and prevent palmitate-induced insulin resistance via AMP-activated protein kinase (AMPK)-dependent pathway that involves partial restoration of insulin-stimulated translocation of GLUT4." (PMID 35011414, 2021). "Therefore, while TMAO is generally associated with worsened insulin resistance and elevated blood glucose levels, there is molecular evidence for beneficial and deleterious TMAO effects on insulin signaling at target tissues." (PMID 34445033, 2021). "Thus as glucose tolerance gradually worsened in FDRs, the insulin levels and insulin resistance were also observed to rise progressively following the natural pathway of the disease." (PMID 34134670, 2021). "We have no clinical data on insulin sensitivity; since liraglutide may play a role in reducing insulin resistance and endothelial dysfunction the metabolic changes between groups may be explained by changes in insulin sensitivity evoked by liraglutide." (PMID 34920733, 2021). "The same authors found that in the HFD group, the OGTT area under the curve (AUC), serum insulin level, homeostatic model assessment for Insulin Resistance (HOMA-IR), and hepatic gene expression of G6Pase (an enzyme involved in glucose production) were significantly higher than in the normal group." (PMID 34065217, 2021). "However, in type 2 diabetes the PI3K/Akt pathway is damaged in various tissues as the result of insulin resistance, and in turn insulin resistance exacerbates the PI3K/Akt pathway, forming a vicious circle." (PMID 33467194, 2021). "This is in agreement with a large cohort study which showed that obese individuals may develop diabetes type 2 predominantly through insulin resistance rather through impaired insulin secretion." (PMID 34601490, 2021). "In an early stage in the progression of T2D, a period of normal and near-normal glycemia is observed for the reason of compensation of pancreatic β-cells by hypersecretion of insulin, and the pancreas tries to compensate for insulin resistance by increasing β-cell mass." (PMID 34358068, 2021). "Female iAsF1 mice showed normal insulin levels, suggesting a potential insulin resistance that may underscore the glucose intolerance phenotype." (PMID 33854880, 2021). "Insulin resistance is one of the early symptoms and core characteristics of T2D and characterized by a reduced physiological response of target tissues to normal insulin levels and leads to reduced glucose utilization in muscle and fat, as well as increased liver glycogenogenesis." (PMID 34272768, 2021). "Of note, cachectic cancer patients suffer of insulin resistance and administration of insulin or insulin sensitizers may reduce muscle wasting." (PMID 33401549, 2021).
Insulin resistance (continued). "TXNIP is a mediator of insulin resistance in liver, skeletal muscle and adipose tissue, and impaired pancreatic beta-cell insulin secretion and TNFα decreases insulin receptor signaling in adipose tissue and skeletal muscle, particularly prior to development of T2DM." (PMID 34371884, 2021). "More studies are needed to utilize more acceptable insulin resistance models like Homeostatic Model Assessment (HOMA) or Quantitative insulin sensitivity check index (QUICKI) to investigate the contribution of insulin resistance on disease severity and mortality in CoVID-19 patients." (PMID 33390183, 2021). "For instance, in addition to the impact of uric acid on endothelial nitric oxide, hyperuricemia increases insulin resistance, which could result in elevations in circulating insulin following consumption of a caffeinated soft drink sweetened with HFCS." (PMID 34676680, 2021). "Dephosphorylation of tyrosine residues of IRS-1 and Akt may inactivate the entire process of insulin signaling, leading to insulin resistance." (PMID 34884501, 2021). "Supplementing berberine (BBR) can reverse the mitochondrial dysfunction caused by high-fat diet (HFD) and skeletal muscle hyperglycemia and can improve insulin sensitivity in rodent models of insulin resistance, partly due to increased mitochondrial biosynthesis." (PMID 34441631, 2021). "Furthermore, the increased body fat and visceral fat of postmenopausal women with normal aging results in an altered expression of adiponectin, which is involved in the regulation of insulin sensitivity, resulting in increased insulin resistance." (PMID 34356226, 2021). "Furthermore, non-carboxylated osteocalcin regulates glucose homeostasis by increasing insulin secretion and decreasing insulin resistance." (PMID 33911128, 2021). "The results suggest that RDW may be more important in augmenting insulin secretion than in insulin resistance." (PMID 33413319, 2021). "Fasting insulin concentration and insulin resistance index improved significantly (p < 0.001)." (PMID 34063446, 2021). "We then tested the effects of EPS on insulin signaling after palmitate-induced insulin resistance." (PMID 34659107, 2021). "Reduced sensitivity of cells to insulin leads to the development of insulin resistance." (PMID 34804684, 2021). "Clinical follow‐up studies have demonstrated that elevated serum uric acid is a strong independent risk factor for insulin resistance, and ours and others’ previous studies have revealed that high uric acid (HUA) evokes insulin resistance in cardiomyocytes, adipocytes, muscle and liver." (PMID 34053175, 2021). "The majority of the available research demonstrates that intermittent fasting is effective at reducing body weight, decreasing fasting glucose, decreasing fasting insulin, reducing insulin resistance, decreasing levels of leptin, and increasing levels of adiponectin." (PMID 33531076, 2021). "Similarly the upregulation of SREBF1 which is known to modulate insulin sensitivity is in line with the literature showing that radiation exposure can lead to insulin resistance." (PMID 33920039, 2021). "Type 2 diabetes (T2D), one of the most prevalent noncommunicable diseases, is often preceded by insulin resistance (IR), which underlies the inability of tissues to respond to insulin and leads to disturbed metabolic homeostasis." (PMID 34205752, 2021). "The >2-fold elevation of plasma insulin levels in the clamped NMN + OLE group caused a substantial improvement in glucose tolerance although oleate-induced insulin resistance was not ameliorated." (PMID 34948019, 2021). "Even in subjects with no MetS components, those with CAP ≥ 238 dB/m had higher BMI, waist and neck circumferences, waist-to-hip ratio, fasting insulin, uric acid, triglyceride, white blood cell count, and indices of insulin resistance, whereas their adiponectin and eGFR were lower." (PMID 35173677, 2021).